TNF (tumor necrosis factor)
Diseases named in the same sentence as TNF in open-access papers (continued):
Sharing a sentence is not in itself a finding about the gene and the disease.
glucose metabolism disorders (11 papers, 2009 to 2025). "Elevated concentrations of CRP, IL-6, and TNF with suboptimal VD levels have been associated with an increased risk of cardiovascular events, glucose metabolism disorders, neurodegenerative diseases, and overall mortality." (PMID 37175418, 2023). "TNF-α is another major pro-inflammatory cytokine that enhances the risk of atherosclerotic thickening causing triglyceride and glucose metabolism disorders and elevating the risk of recurrent ACS disease." (PMID 35563407, 2022). "The relationship between elevated serum hs-CRP level and glucose metabolism disorders may be intermediated by increased secretion of TNF-α and IL-6." (PMID 28361994, 2017). "TNF-α and IL-6 levels have been reported by others to be increased in patients with OSA and in those with left ventricular diastolic dysfunction and glucose metabolism disorders." (PMID 21122092, 2010).
Hemophagocytosis (11 papers, 2014 to 2025). Phagocytosis by macrophages of erythrocytes, leukocytes, platelets, and their precursors in bone marrow and other tissues. "In these cases, IFN-γ and TNF-α inhibit the hematopoietic function of bone marrow, and the function of activated macrophages is out of control, together resulting in hemophagocytosis." (PMID 33413556, 2021). "Activated immune cells have been established to release proinflammatory cytokines (IFN-γ, TNF-α, IL-1, IL-6, TNF-α, and so on), leading to high levels of macrophage activation, which, in turn, might cause hemophagocytosis, tissue damage, organ failure, and other inflammatory manifestations." (PMID 41020231, 2025). "It is induced by an extreme immune activation of cytotoxic T-lymphocytes, natural killer (NK) cell and macrophages with an excessive cytokine production of tumor necrosis factor α (TNF-α) and interferon γ (IFN-γ), which is followed by hemophagocytosis." (PMID 32164748, 2020). "Hemophagocytosis plays a quantitative rolethat may not be important in these cytopenias which aremore related to the secretion of TNF-α as well as IFN-γ." (PMID 31648438, 2019).
Hydrocephalus (11 papers, 2008 to 2025). Hydrocephalus is an active distension of the ventricular system of the brain resulting from inadequate passage of CSF from its point of production within the cerebral ventricles to its point of absorption into the systemic circulation. "In human foetuses with hydrocephalus and in hyh mice, there are high levels of the proinflammatory cytokine TNFα, which is associated with reactive astrocytes in the periventricular white matter." (PMID 34215285, 2021). "Moreover, higher IL6 expression and lower TNF expression were associated with preoperative hydrocephalus." (PMID 38965454, 2024). "This inflammatory milieu generates free radicals and pro-inflammatory cytokines such as interleukin (IL)-6, IL-4, tumor necrosis factor-α (TNFα), and transforming growth factor-β1 (TGFβ1), which contribute to the development and progression of hydrocephalus." (PMID 37794877, 2023). "In patients with possible normal pressure hydrocephalus, median ventricular CSF concentrations were reported for IL-8 (19.1 [11.0] pg/mL), TNF-alpha, and CCL2 (758 [264.0] pg/mL)." (PMID 34439789, 2021). "TNFα has been found produced by periventricular reactive astrocytes in the hyh mouse and human fetuses with hydrocephalus." (PMID 32183876, 2020). "Furthermore, we assessed several proinflammatory cytokines, such as IL‐1β, IL‐6 and TNF‐α, by Western blotting, and the results showed that the expression levels of IL‐1β, IL‐6 and TNF‐α in the cortex and hippocampus were increased in the hydrocephalus group compared with the sham group at 28 days." (PMID 34374150, 2021). "We observed that ICH patients with hydrocephalus had higher levels of IL-6, IL-8, IL-10, and TNF-α in their CSF compared to those without hydrocephalus." (PMID 38167007, 2024). "In a hydrocephalus mouse model, Nec‐1 and GSK872 reduce necrotic cell death, effectively inhibit the phosphorylation of RIP3 and MLKL, and reduce the levels of inflammatory factors such as IL‐1β, IL‐6 and TNF‐α in the cortex and hippocampus." (PMID 34374150, 2021). "Furthermore, the aggregation of choroid plexus (ChP) macrophages can amplify NF-κB signaling in epithelial cells through the tumor necrosis factor alpha/tumor necrosis factor receptor 1 (TNF-α/TNFR1) pathway, promoting excessive cerebrospinal fluid (CSF) secretion and worsening hydrocephalus." (PMID 40722587, 2025).
immunotoxicity (11 papers, 2014 to 2025). "Recently, it was also reported that dibutyltin, another organotin compound that causes severe immunotoxicity and developmental toxicity in animals, increased iNOS, TNF-α, and IL-6 mRNA levels in BV-2 cells." (PMID 26221064, 2015). "Moreover, PVC MP pose a very serious threat to the human organism, as they can circulate in the body and their long exposure can cause immunotoxicity to the cells stimulating the release of interleukin 6 (IL-6) and tumor necrosis factor-α (TNF-α)." (PMID 34069160, 2021). "A study showed that carbon nanotubes induce immunotoxicity, and quercetin can ameliorate its induced immunotoxicity, inflammation, and oxidative response through mechanisms such as decreasing TNF-α and IL6 concentrations, and mRNA levels." (PMID 39434897, 2024). "Acute cytotoxicity was tested by measuring release of lactate dehydrogenase (LDH) and immunotoxicity was determined by measuring secretion of pro-inflammatory cytokines interleukin-1-beta (IL-1β) and tumor necrosis factor-alpha (TNF-α)." (PMID 25473947, 2014). "Similarly, Cd immunotoxicity was evident from elevated TNF-α protein levels following Cd exposure within brain, liver, and ovary tissue of zebrafish." (PMID 39199178, 2024). "Significant increases in immune-related protein indicators (NF-κB, TNF-α, IL-1β and TLR4) were detected in our study, indicating that 6:2 FTSA amplifies the inflammatory damage profile and induces organismal immunotoxicity in zebrafish larvae." (PMID 37235273, 2023). "In the present study, we determined the levels of two inflammatory cytokines, including TNF-α and MIP-2, to evaluate immunotoxicity in BALF of rats exposed to CuO NP." (PMID 36362054, 2022). "Similarly, Wang and colleagues reported that T-2 induced the overexpression of proinflammatory genes and upregulated the mRNA expression of TNFα, IL-1β, and IL-6, leading to the activation of the JAK-STAT signaling pathway contributing to immunotoxicity." (PMID 40864073, 2025).
neuritis (11 papers, 2016 to 2025). A neuropathy arising from inflammation of one or more nerves. "Excessive activation of microglia is profoundly implicated in the neuroinflammation via producing a cascade of inflammatory mediators such as iNOS/NO, IL-1β, IL-6, and TNF-α, which further result in neuritis, immune response, damage of neurons, and cause cognitive dysfunction." (PMID 34485533, 2021). "It has been proposed that M. leprae induces Schwann cell death by a pathway that involves proinflammatory cytokines, and TNF-α has already been identified in the nerve biopsies of patients with neuritis." (PMID 38116016, 2023). "TNF involvement was also seen in reactive patients with neuritis, who showed an increased expression of TNF, the TNF receptor, and TNF-converting enzyme in nerve biopsies." (PMID 35281455, 2022). "IL‐6, a pleiotropic proinflammatory factor, plays an important role in chronic inflammation and neuritis; TNF‐α is also involved in the inflammatory response by inducing NF‐κB activation." (PMID 29670828, 2018). "Therefore, the expressions of MyD88, NF‐κB, and TNF‐α reflect the severity of neuritis and the expression of the HMGB1–TLR4 axis." (PMID 29670828, 2018). "For example, PTE reduces the expression of pro-inflammatory cytokines such as interleukin (IL)-6 and tumor necrosis factor-α (TNF-α) in LPS-induced models, exhibiting anti-neuritis effects in rats." (PMID 39943187, 2025). "Koumine inhibits the overexpression of interleukin 6 (IL-6), IL-1, and tumor necrosis factor (TNF) in tumors, showing anti-neuritis effects." (PMID 34885727, 2021). "The inhibitory effect of SYS18 on neuritis may be related to the protection of BBB integrity and the reduction of TNF‐α and IL‐1β in the brain." (PMID 39500736, 2024).
nicotine addiction (11 papers, 2015 to 2025). "The results of KEGG enrichment show that ten different genes were enriched, including gap junction, Toll-like receptor signaling pathway, TNF signaling pathway, and nicotine addiction." (PMID 35873623, 2022). "Among these pathways, neuroactive ligand-receptor interaction, TNF signaling pathway, Phenylalanine metabolism, Nicotine addiction, IL-17 signaling pathway, Morphine addiction, and Cholinergic synapse are related to morphine-induced tolerance." (PMID 34512242, 2021). "Meanwhile, we also found these genes mainly participated in seven categories of pathways, including TNF signaling pathway, IL-17 signaling pathway, neuroactive ligand-receptor interaction, Phenylalanine metabolism, Nicotine addiction, Morphine addiction, and Cholinergic synapse." (PMID 34512242, 2021). "For nicotine addiction, TNF, ERK1/2 and Akt had the most edges (85, 76, and 53, respectively)." (PMID 26044620, 2015). "Reported outcomes include pulmonary function (e.g., FEV1), inflammatory and oxidative stress biomarkers (e.g., TNF-α, IL-6, CRP, 8-OHdG), nicotine dependence scores, salivary cotinine levels, oral health indices, and other exposure-related markers." (PMID 41281023, 2025). "Further KEGG pathways analysis showed these genes were enriched in pathways involving extracellular matrix (ECM)-receptor interaction, tumor necrosis factor (TNF) signaling, nicotine addiction, chemical carcinogenesis-reactive oxygen species, and others." (PMID 35768804, 2022). "Furthermore, MDD, morphine dependence, and nicotine dependence share pro-inflammatory cytokines interleukin 6 (IL6), interleukin 1B (IL1B), and tumor necrosis factor (TNF) with progeria syndrome." (PMID 38926475, 2024).
paroxysmal AF (11 papers, 2017 to 2026). "Furthermore, TNF-α levels seem to be elevated with persistence of AF: mean TNF-α levels are higher in people with persistent or permanent AF than paroxysmal AF." (PMID 41590667, 2026). "Serum TNF-α levels are significantly higher in patients with AF compared to those in sinus rhythm and levels are higher in those with persistent and permanent AF than in patients with paroxysmal AF." (PMID 39030470, 2024).
Peritoneal Fibrosis (11 papers, 2014 to 2025). Disorder characterized by a wide range of structural changes in PERITONEUM, resulting from fibrogenic or inflammatory processes. "LPS exposure in mouse peritoneum initiates the release of several inflammatory cytokines, including IL-1β, IL-6, and TNF-α, leading to further peritoneal fibrosis." (PMID 39728104, 2024). "According to these results, we hypothesized that AST inhibits peritoneal fibrosis (PF) through suppression of TNF/TGF expression by quenching ROS." (PMID 28926603, 2017). "Since an abundant expression of inflammatory cytokines and chemokines is essential for the development and progression of peritoneal fibrosis, we further evaluated the effect of TA on the expression of some inflammatory cytokines and chemokines, including IL-6, IL-1β, TNF-α and MCP-1 by ELISA." (PMID 29179471, 2017). "Beyond TGF-β/Smad signaling, SIRT1 mitigates inflammation through deacetylation of the NF-κB p65 subunit, thereby reducing the expression of tumor necrosis factor α (TNF-α) and interleukin 6 (IL-6), both critical mediators of EMT and peritoneal fibrosis." (PMID 41009597, 2025). "Taken together, between the two PDFs, there are outspoken differences in levels of TGFβ1, TNFα, INFγ, and MIP-1β suggesting that macrophages played a crucial role over other cell types in modulating the response of BLS on peritoneal fibrosis and angiogenesis." (PMID 29728994, 2018). "Nintedanib attenuates the expression of cytokines/chemokines, including TNF-α, IL-1β, and IL-6, monocyte chemoattractant protein-1 (MCP-1) and prevents the macrophages infiltration to the injured peritoneum in chlorhexidine gluconate (CG)-induced peritoneal fibrosis." (PMID 35164664, 2022). "We previously reported peritoneal fibrosis (PF) induced by chlorhexidine (CH) was significantly suppressed in PF rats with AST supplemented diet, and the level of 8-hydroxy-2'-deoxyguanosine (8-OHdG) and cytokine such as TNFα and TGFβ were suppressed in the peritoneum." (PMID 28926603, 2017). "Thus, TGFβ1 promotes peritoneal fibrosis and dysfunction, PDGF-B promotes angiogenesis, IL-6 and its soluble receptor (sIL-6R) control the pattern of leukocyte recruitment during peritoneal inflammation and the IFNγ/TNFα combination promotes mesothelial cell apoptosis." (PMID 24599047, 2014).
pituitary adenomas (11 papers, 2010 to 2025). "Similarly, in pituitary adenomas, TNF‐α has been confirmed to be associated with tumor invasion, exhibiting elevated expression in invasive pituitary adenomas." (PMID 38739004, 2024). "In bone-invasive pituitary adenomas, TNFα activates the MAPK pathway autocrinely and promotes MMP9 expression, further accelerating membrane invasion." (PMID 40351428, 2025). "More importantly, we validated a drug that can inhibit the biological effects of TNFα in promoting the proliferation and invasion of pituitary adenomas, providing a novel direction for the treatment of BIPA." (PMID 38739004, 2024). "The excessive TNFα acts on pituitary adenoma cells in an autocrine manner, activating the MAPK signaling pathway and increasing the expression of MMP9." (PMID 38739004, 2024). "Bone‐invasive pituitary adenoma secretes higher levels of TNF‐α, which then acts on itself in an autocrine manner, activating the MAPK pathway and promoting the expression of MMP9, thereby accelerating the membrane invasion process." (PMID 38739004, 2024). "We have found that TNF‐α promotes bone invasion by facilitating the differentiation of osteoclasts, however, before bone‐invasive pituitary adenoma invades bone tissue, it needs to penetrate the dura mater, and this mechanism is not yet clear." (PMID 38739004, 2024). "The current study aimed to investigate the role of MEG8/miR-454-3p/TNF-α in bone-invasive pituitary adenomas (BIPAs)." (PMID 34016788, 2021). "Combined with our previous research, the mechanism of TNF-α affecting pituitary adenoma to invade bone is more perfect." (PMID 34016788, 2021). "The correlation between MEG8 and miR-454-3p expression, miR-454-3p and TNF-α expression, MEG8 and TNF-α in pituitary adenomas were analyzed according to RT-qPCR results." (PMID 34016788, 2021). "Hemorrhagic pituitary adenomas displayed higher protein and mRNA levels of TNF-α, vascular endothelial growth factor (VEGF) and matrix metalloproteinase-9 (MMP-9) compared with those of non-hemorrhagic tumors." (PMID 21747731, 2011). "In the present study, the possible correlation between TNF-α and hemorrhage within pituitary adenomas was investigated." (PMID 21747731, 2011). "Taken together, our results show that TNF-α significantly correlates with intratumoral hemorrhage in pituitary adenomas and induces pituitary adenoma hemorrhage through up-regulation of VEGF and MMP-9." (PMID 21747731, 2011). "SPD304 significantly inhibits the effect of TNF‐α and may be applied in the clinical treatment of bone‐invasive pituitary adenoma." (PMID 38739004, 2024). "In this study, we further confirmed that the secretion of TNFα from BIPA not only promotes bone invasion by facilitating the differentiation of osteoclasts but also acts on pituitary adenoma cells in an autocrine manner, enhancing their proliferation, invasion, and migration capabilities." (PMID 38739004, 2024). "TNF-α also may be an important regulator of hemorrhagic transformation in pituitary adenomas indicated by the finding that hemorrhagic pituitary adenomas displayed higher protein and mRNA levels of TNF-α." (PMID 34090476, 2021). "TNF-α level is increased in invasive pituitary adenomas such as the one diagnosed in our patient." (PMID 31202268, 2019). "Based on these findings, our study demonstrates that TNF-α may play a role in the development of hemorrhage within pituitary adenomas." (PMID 21747731, 2011). "Additionally, TNF-α administration caused hemorrhagic transformation and enhanced VEGF and MMP-9 expression in MMQ pituitary adenoma cell xenografts in mice." (PMID 21747731, 2011). "Here we show that TNF-α may be an important regulator of hemorrhagic transformation in pituitary adenomas." (PMID 21747731, 2011). "This study suggests that TNF-α may play a role in the development of intratumoral hemorrhage in pituitary adenomas via up-regulation of VEGF and MMP-9." (PMID 21747731, 2011).
pituitary adenomas (continued). "Exposure of MMQ pituitary adenoma cells to TNF-α induced VEGF and MMP-9 expression in vitro." (PMID 21747731, 2011). "SPD304, as a small‐molecule inhibitor of TNFα, can inhibit the upregulation of TNFα on MAPK and MMP9, thereby reducing the membrane invasion capability and bone invasion ability of pituitary adenoma cells." (PMID 38739004, 2024). "A study involving 40 cases each of invasive pituitary adenoma (IPA) and non-invasive pituitary adenoma (NIPA) used the streptavidin peroxidase immunohistochemical method to examine TNF-α and IL-6 expression." (PMID 38275385, 2023). "Recent studies have provided that the IFN, the ILs and the tumor necrosis factor TNF play a key role in the differentiation of the pituitary gland and in the oncogenesis of pituitary adenomas/PitNets." (PMID 36658300, 2023). "We evaluated TNF-α, VEGF and MMP-9 expression in surgical specimens of hemorrhagic and non-hemorrhagic pituitary adenomas." (PMID 21747731, 2011).
POEMS syndrome (11 papers, 2012 to 2025). POEMS syndrome is a paraneoplastic syndrome characterized by polyradiculoneuropathy (P), organomegaly (O), endocrinopathy (E), clonal plasma cell disorder (M), and skin changes (S). "Multiple proinflammatory cytokines such as interleukin-1, TNF-α, and IL-6 are upregulated in POEMS syndrome." (PMID 27068711, 2016). "Second, in POEMS syndrome there is overproduction of proinflammatory cytokines, including TNFα, IL1β, IL10, IL6, VEGF, similarly to what is observed in MCD and KICS, suggesting that these three clinical entities partially overlap." (PMID 25607954, 2015). "In addition, thalidomide and lenalidomide, which have anti-VEGF and anti-TNF effects, have been used in the treatment of POEMS syndrome." (PMID 39691601, 2024). "Besides VEGF, other pro-angiogenic and pro-inflammatory factors, such as basic fibroblast growth factor, hepatocyte growth factor, tumor necrosis factor-α, IL-6, and IL-12, are elevated in POEMS syndrome." (PMID 34025681, 2021). "The pathogenesis of POEMS syndrome is not well understood, but overproduction of proinflammatory cytokines, such as interleukin (IL)-1β, IL-6, tumor necrosis factor (TNF)-α, and vascular endothelial growth factor (VEGF), has been reported and could play very important etiological roles." (PMID 23251183, 2012). "POEMS syndrome, on the other hand, is characterized by significantly elevated VEGF levels, along with increased inflammatory cytokines such as IL‐1β, IL‐6, and TNF-α." (PMID 41293360, 2025). "Furthermore, patients with POEMS syndrome often demonstrate elevated levels of VEGF, TNF-α and interferon-γ (IFN-γ), cytokines that may contribute to erythroid suppression via aberrant immune activation." (PMID 41221261, 2025). "Finally, pro-inflammatory cytokines, such as tumor TNF-α, IL-6, and IL-12, which are upregulated in POEMS syndrome, were not evaluated, and this should be performed in future studies." (PMID 34167480, 2021). "The pathogenesis of POEMS syndrome is not well understood but it is thought to involve overproduction of proinflammatory cytokines, such as vascular endothelial growth factor (VEGF), interleukin-1 beta (IL-1B), interleukin-6 (IL-6), and tumor necrosis factor-alpha (TNF-alpha)." (PMID 34692278, 2021).